FMR1 (fragile X messenger ribonucleoprotein 1)
Diseases named in the same sentence as FMR1 in open-access papers (continued):
Sharing a sentence is not in itself a finding about the gene and the disease.
fragile X syndrome (continued). "The FMR1 gene is well-described in humans in the context of disturbed fertility in women and the associated Fragile X Syndrome (FXS)." (PMID 39300329, 2024). "Fragile X Syndrome (FXS) is an X-linked disorder leading to the loss of expression of FMR1-protein product, FMRP." (PMID 37205401, 2023). "Impaired FMR1 function due to addition of trinucleotide repeat expansion in the promoter region causes fragile-X syndrome, a mental retardation condition." (PMID 36758804, 2023). "Fragile X Messenger Ribonucleoprotein 1 (FMR1) gene mutations lead to fragile X syndrome, cognitive disorders, and, in some individuals, scoliosis and craniofacial abnormalities." (PMID 37193680, 2023). "Fragile X syndrome, which is caused by mutation of Fragile X mental retardation 1 (FMR1) gene, is a common neurodevelopmental disorder characterized by intellectual disability with autism." (PMID 36768393, 2023). "Research on genotype–phenotype associations in FMR1 has focused primarily on those with fragile X syndrome (FXS), the premutation, and to a lesser extent the gray zone." (PMID 37681869, 2023). "Mutations in the Fragile X Messenger Ribonucleoprotein 1 (FMR1) gene cause Fragile X Syndrome (FXS), the most common genetic form of intellectual disability." (PMID 37542065, 2023). "Fragile X syndrome (FXS) is a neurodevelopmental disorder that is caused by an X-linked mutation in the FMR1 gene." (PMID 36833432, 2023). "Fragile X syndrome is caused by a CGG repeat expansion in the 5′ untranslated region (UTR) of the fragile X messenger ribonucleoprotein 1 (FMR1) gene located at Xq27.3." (PMID 36969493, 2023). "CGG repeat expansion in 5′ UTR of FMR1 gene is the genetic cause of fragile X syndrome (FXS) and fragile X-associated tremor/ataxia syndrome (FXTAS)." (PMID 36768697, 2023). "Fragile X messenger ribonucleoprotein 1 (FMR1) is an mRNA binding protein mutated in fragile X syndrome, which is the most common cause of inherited intellectual disability and shares large degree of similarities in symptomatology with ASD." (PMID 37547211, 2023). "The subject 4 had a FMR1 full mutation, being positive for Fragile X-syndrome (FXS) testing (> 200 CGG repeats in the 5′-untranslated region of FMR-1 gene) along with a variant in KMT2C, suggesting a putative digenic model." (PMID 38025430, 2023). "The FMR1 FM causes Fragile X syndrome (FXS), the most common form of inherited intellectual disability (ID) and monogenic cause of autism spectrum disorder (ASD)." (PMID 37443745, 2023). "Fragile X syndrome (FraX) is the most common form of congenital mental retardation caused by the transcriptional silencing of the Fragile X mental retardation 1 (Fmr1) gene." (PMID 37935354, 2023). "Fragile X mental retardation 1 (Fmr1) knockout mice are the most investigated model for the human fragile X syndrome, the most common cause for intellectual disability and ASD in human." (PMID 36970280, 2023). "In this context, it is important to consider several syndromes with ASD characteristics, such as Fragile X syndrome, for which the causative gene (Fmr1) has been identified and the pathophysiology is becoming clearer." (PMID 36846233, 2023). "Mutations in the Fragile X Messenger Ribonucleoprotein 1 (FMR1) gene are linked to Fragile X Syndrome, the most common monogenic cause of intellectual disability and autism." (PMID 37542065, 2023). "Expansion of a CGG repeat in the Fragile X Messenger Ribonucleoprotein 1 (FMR1) gene on the X chromosome is the cause of Fragile X Syndrome (FXS)." (PMID 37628570, 2023).
fragile X syndrome (continued). "Pathogenic variants in the coding region of FMR1 are causal in <1% of Fragile X syndrome cases and only a few dozen patients with point variants have been reported in the literature to date." (PMID 36980980, 2023). "There is a report on Iranian patients with an altered expression of SLITRK4 associated with fragile X syndrome caused by a repeat expansion in the 5′ untranslated region of the FMR1 gene at the same chromosomal location." (PMID 37891789, 2023). "Mutations in the Fragile X Messenger Ribonucleoprotein 1 (FMR1) gene cause Fragile X Syndrome, the most common monogenic cause of intellectual disability." (PMID 36909303, 2023). "On the contrary, in fragile X syndrome, despite a smaller n, we identified total abrogation of FMR1 expression, as expected, in both cases of the full mutation and gene deletion." (PMID 37252957, 2023). "In FMR1 full mutation, the Fragile X Syndrome is caused by the absence of the FMR1 protein (FMRP) and its functioning." (PMID 36983968, 2023). "Fragile X syndrome is caused by an abnormality in the Fragile X messenger ribonucleoprotein 1 (FMR1) gene." (PMID 37200782, 2023). "Another interesting gene downstream of Pax6 is Fmr1, a causative gene for fragile X syndrome, one of the neurodevelopmental disorders." (PMID 35682795, 2022). "A recently identified target for PDE4 inhibitors is fragile X syndrome, a genetic disease caused by the alteration of FMR1 gene." (PMID 35956914, 2022). "Fragile X syndrome (FXS) is a neurodevelopmental disorder resulting from a trinucleotide (CGG) repeat mutation in the fragile X mental retardation (FMR1) gene, which codes for the Fragile X mental retardation protein (FMRP)." (PMID 35089938, 2022). "For example, the (CCG)n repeats in the promoter region of the FMR1 gene were found to disrupt the chromatin topology domain (TAD) structure and DNA methylation, thereby altering the expression of FMR1 and causing Fragile X Syndrome." (PMID 35034641, 2022). "Fragile X syndrome (FXS) is an X-linked disorder that results from an expansion of a cytosine-guanine-guanine (CGG) sequence in the promoter region of the FMR1 gene, located at Xq27.3, from the typical 35 or so repeats to greater than 200 repeats." (PMID 35432025, 2022). "For example, the FMR1 gene and the FMRP protein (product of the FMR1 gene) underlie Fragile X Syndrome, which is the most known genetic monogenic cause of ASD." (PMID 35923445, 2022). "For instance, several genetic mutations related to ASD were performed in the Drosophila such as the FMR1 mutation mimicking the Fragile X Syndrome, which is the most frequent monogenic mutation associated to ASD." (PMID 36421705, 2022). "Mutations in the FMR1 gene are responsible for fragile X syndrome (FXS) and contribute to 8% of ASD cases." (PMID 35493332, 2022). "Fragile X syndrome (FXS) is an X-linked disorder caused by an expansion of a cytosine–guanine–guanine (CGG) trinucleotide sequence on the FMR1 gene to more than 200 repeats." (PMID 36778100, 2022). "The most common mutation causing fragile X syndrome is the expansion of the trinucleotide CGG repeats in FMR1 first exon into full mutation (more than 200 repeats) leading to transcription repression." (PMID 35641906, 2022). "Mutations in FMR1 gene are causing human fragile X syndrome (FXS), which is probably the most common heritable foundation of autism disorders and mental retardation." (PMID 35269756, 2022). "Based on the literature, FMR1 is definitely related to fragile X syndrome (FXS), which is an X-linked disorder; however, few studies have focused on cancers." (PMID 35351128, 2022).
fragile X syndrome (continued). "Fragile X syndrome is caused by FMR1 gene disruption on the X chromosome that prevents the expression of FMRP, which is involved in synaptic development and plasticity." (PMID 35456477, 2022). "Fragile X syndrome is caused by a mutation in FMR1, which encodes a fragile X mental retardation protein." (PMID 35625052, 2022). "For example, Fragile X syndrome is caused by expansion of (CGG)n repeats within the 5′ UTR of the FMR1 locus." (PMID 35853874, 2022). "In this study, fragile X syndrome (FXS) testing identified mosaic FMR1 full mutation alleles in a male patient." (PMID 34773222, 2022). "FMR1 dysfunction in humans is associated with Fragile X Syndrome, a neurodevelopmental disorder that exhibits social deficits." (PMID 36138431, 2022). "A considerable expansion of this repeat can silence the expression of FMR1, potentially resulting in the range of characteristics associated with fragile X syndrome." (PMID 35741066, 2022). "The first expansions, identified on chromosome X in 1991, were CGG repeats in the 5′ untranslated region of the FMR1 gene (MIM:309550) that are the underlying cause of fragile X syndrome (FXS [MIM: 300624])." (PMID 35794169, 2022). "The CYFIP1 gene encodes a protein product that interacts with FMRP, the protein coded by the FMR1 gene causing fragile X syndrome." (PMID 35787815, 2022). "Fragile X syndrome (FXS) is a monogenic developmental disorder caused by mutation of the fragile X mental retardation 1 (FMR1) gene." (PMID 35582646, 2022). "For example, the gene Fmr1 encodes the Fragile X Messenger Ribonucleoprotein (FMRP) whose dysfunction is causative for Fragile X Syndrome, which is characterized by many different aberrant neuronal phenotypes including intellectual disability." (PMID 36648904, 2022). "Most efforts to understand the FMR1 epigenetic marks have been towards the characterization of the epigenetic modifications associated with the gene silencing mechanism leading to fragile X syndrome." (PMID 35641906, 2022). "Studies aimed at understanding FMR1 premutation-associated risk as manifested in mothers of children with fragile X syndrome are highly important because clinical problems in mothers impact outcomes for both the mother and her children." (PMID 35026985, 2022). "Fragile X syndrome is caused by an elongated CGG trinucleotide repeat on the FMR1 gene, located on the X chromosome." (PMID 36081464, 2022). "FMRP is encoded by the Fmr1 gene, which, when mutated, is associated with Fragile-X Syndrome (FXS), the most common heritable form of intellectual disability and autism spectrum disorder." (PMID 34805187, 2021). "For example, up to 3% of individuals have fragile X syndrome (FXS) caused by mutations in the FMR1 gene—a gene that regulates about 6000 mRNAs in the brain and maintains synaptic plasticity." (PMID 34827633, 2021). "Despite these limitations, however, the final sample produced a rich and diverse dataset, highlighting a range of perspectives and experiences with fragile X syndrome and FMR1‐associated conditions." (PMID 33184995, 2021). "Two genes causal for fragile x syndrome, FMR1 and FXR2, displayed a strong lysosome phenotype together with increased tau aggregation upon CRISPR loss of function." (PMID 33536571, 2021). "When modeling fragile X syndrome in mice (FMR1 knockout), mutations of the CPEB1 gene was found to reduce the pathological processes associated with the syndrome." (PMID 33789753, 2021). "Fragile X syndrome (FXS) is a neurodevelopmental disorder caused by the transcriptional silencing of the Fragile X mental retardation 1 (Fmr1) gene, which leads to the loss of the Fragile X Mental Retardation Protein (FMRP)." (PMID 34645383, 2021). "FMR1 associated with fragile X syndrome was included on the BabyGenes panel and placed in ASQM Category 2 by our group." (PMID 33781310, 2021).
fragile X syndrome (continued). "This study described the identification of a trinucleotide repetitive region, a CGG repeat tract located at the 5′ untranslated region of FMRP translational regulator 1 gene (FMR1) implicated in Fragile X syndrome (FXS)." (PMID 34930158, 2021). "FMRP, encoded by the FMR1 gene, is transcriptionally silenced in Fragile X syndrome, which is the leading genetic cause of ASD." (PMID 33802132, 2021). "Fragile X syndrome, caused by loss of function of the FMR1 gene, is thought to be one of the most common inherited genetic causes of ID and ASD." (PMID 33681094, 2021). "An estimated 1 in 291 women in western countries carry the FMR1 premutation that causes fragile X syndrome." (PMID 33184995, 2021). "Expansions of a CGG repeat in the FMR1 gene exceeding 200 bp produce a full mutation that causes the fragile X syndrome (FXS), characterized by autistic-behaviors and intellectual disability." (PMID 33340060, 2021). "Fragile X Syndrome is a neuro-developmental disorder caused by the silencing of the FMR1 gene, resulting in the loss of its protein product, FMRP." (PMID 34566717, 2021). "Transcriptional silencing of FMR1 is the most common genetic cause of fragile X syndrome (FXS), the most commonly inherited form of MR in humans." (PMID 33796531, 2021). "It is the loss of FMR1 gene expression, the opposite mechanism with respect to the associated conditions, which is responsible for the Fragile X Syndrome phenotype." (PMID 34300485, 2021). "Common examples are fragile X syndrome (FXS) caused by a mutation in the FMR1 gene and tuberous sclerosis complex (TSC) caused by a mutation in TSC1 and TSC2 genes." (PMID 33450950, 2021). "Ninety-nine percent of cases of fragile X syndrome are caused by an expansion of the unstable CGG repeat sequence in the 5′ untranslated region (UTR) of the FMR1 gene." (PMID 33681094, 2021). "Fragile X syndrome is caused by the silencing of the Fragile X Mental Retardation gene 1 (FMR1), which is associated to CGG repeat expansion in its 5′UTR region." (PMID 34867203, 2021). "Fragile X syndrome (FXS) is one of the FMR1-associated conditions characterized by a broad spectrum of intellectual and cognitive deficits, including a large constellation of behavioral and physical features." (PMID 34679478, 2021). "FMRP is the gene product of FMR1, which, when mutated, causes fragile X syndrome, the most common monogenic form of intellectual disability." (PMID 33931204, 2021). "Inactivation of the FMR1 (fragile X mental retardation-1) gene underlies fragile X syndrome and results from an increase in the number of CGG repeats in the 5'UTR of the gene." (PMID 33789753, 2021). "Loss-of-function mutations in FMR1 in humans cause Fragile X Syndrome (FXS), the most common inherited form of intellectual disability and leading monogenic cause of ASD." (PMID 34617509, 2021). "FMRP is encoded by the Fmr1 gene, in which mutations cause fragile X syndrome, a mental retardation disorder." (PMID 31978946, 2020). "A triplet repeat expansion leading to transcriptional silencing of the FMR1 gene results in fragile X syndrome (FXS), which is a common cause of inherited intellectual disability and autism." (PMID 31991700, 2020). "Fragile-X syndrome (FXS) is an X-linked mental retardation disorder resulting from silencing of the FMR1 gene and loss of its protein product, FMRP, an mRNA binding protein that mainly acts as translational repressor." (PMID 32325875, 2020). "Regardless, the aberrant expansion of the CGG trinucleotide repeat at the FMR1 gene that causes Fragile X Syndrome (FXS) is still the most common condition in XLID." (PMID 31906484, 2020). "Fragile X syndrome (FXS) is a neurodevelopmental disorder that is caused by mutations in the FMR1 gene." (PMID 32788572, 2020).
fragile X syndrome (continued). "Fragile X syndrome (FXS) is caused by expansion full mutation (≥200 CGGs) of the fragile X mental retardation 1 (FMR1) gene leading to epigenetic silencing of the gene, resulting in reduction of its product: fragile X mental retardation protein (FMRP)." (PMID 33255214, 2020). "The mutation leading to over 98% of cases of fragile X syndrome is an expansion of an unstable CGG repeat sequence located in the 5′UTR of the FMR1 gene." (PMID 32858868, 2020). "Fragile X syndrome (FXS) is caused by an expansion of a single trinucleotide sequence (CGG) resulting in silencing of FMR1, an X-linked gene coding for fragile X mental retardation protein (FMRP)." (PMID 33519379, 2020). "The KO of Fmr1 gene in mouse (Fmr1−/y) exhibits the primary molecular and behavioral symptoms associated with Fragile X syndrome (FXS), an inherited neurodevelopmental disorder with a wide variety of symptoms characteristic of ASD." (PMID 32620110, 2020). "Fragile X syndrome (FXS) is caused by silencing of the FMR1 gene, which encodes a protein with a critical role in synaptic plasticity." (PMID 33008014, 2020). "Fragile X syndrome (FXS) is a genetic condition associated with the full mutation of the fragile X mental retardation 1 (FMR1) gene." (PMID 32992879, 2020). "Loss or disrupted expression of the FMR1 gene causes fragile X syndrome (FXS), the most common monogenetic form of autism in humans." (PMID 32938458, 2020). "In contrast, longer repeat expansions, more than 200 units, induce silencing of FMR1 mRNA, which results in a lack of FMRP protein, causing the neurodevelopmental Fragile X syndrome." (PMID 33381520, 2020). "Second, repeats generally do not exceed a few hundred (± 200) in fragile X tremor ataxia syndrome (FXTAS; O'Donnell & Warren, 2002) although longer repeats are associated with fragile X syndrome due to FMR1 loss of function." (PMID 31721251, 2020). "The development of animal models has provided the field with important clinical but also molecular information regarding the pathology associated with CGG repeat expansions on FMR1 Fragile X syndrome (FXS), PM carriers and FXTAS." (PMID 32219099, 2020). "Fragile X syndrome is clinically characterized as ID; phenotypically, patients show dysmorphic facial features and protruded ears.FMR1 encodes for a protein that provides RNA stability and plays a key role in brain development and neuronal plasticity." (PMID 31984132, 2020). "CRISPR–Cas9 systems have been used on fragile X syndrome caused by the extension of trinucleotide repeats, which results in deteriorated levels of FMR1 protein and Huntington disease (HD) models." (PMID 31984132, 2020). "The disease gene of fragile X syndrome, FMR1 gene, encodes fragile X mental retardation protein (FMRP)." (PMID 32552710, 2020). "Fxr1 belongs to the same gene family as fragile X mental retardation gene 1 (Fmr1), which is considered the causative gene of fragile X syndrome." (PMID 33463674, 2020). "FragileXmentalretardation1 (FMR1) encoding fragile X mental retardation protein (FMRP) is a well-characterized gene related to a typical neurodevelopmental disorder, Fragile X syndrome (FXS)." (PMID 33323119, 2020). "In humans, mutations in Fragile X Mental Retardation 1 (FMR1) causes Fragile X syndrome, a disease associated with severe cognitive deficits and autism-like behaviors." (PMID 33381506, 2020). "In other aspect, Fragile-X syndrome (MIM#30064) is caused by an expansion repeat of CGG in the 5′ UTR of the FMR1 gene." (PMID 32193494, 2020). "Recently, with the technology of the CRISPR-Cas9 system applied in vivo to laboratory mice, it has become possible to demonstrate that DNA methylation at the FMR1 gene causes the molecular and physiological phenotype of fragile-X syndrome." (PMID 30832291, 2019). "Fragile X syndrome (FXS) is a genetic disorder caused by a trinucleotide CGG expansion within the FMR1 gene located on the X chromosome." (PMID 31354578, 2019).